BRCA2 (BRCA2 DNA repair associated)
Diseases named in the same sentence as BRCA2 in open-access papers (continued):
Sharing a sentence is not in itself a finding about the gene and the disease.
ovarian carcinoma (continued). "Mutations in BRCA1 and BRCA2, tumor suppressor genes, are found in about 50% and 70% of ovarian cancer patients with a family history of ovarian cancer, but 95% of ovarian cancer cases are sporadic." (PMID 30134520, 2018). "We have reported the findings of a methodical review of reported germline variants in BRCA1, BRCA2, and other high-penetrance breast and ovarian cancer susceptibility genes within women of Indian descent." (PMID 35693198, 2018). "BRCA1 mutation carriers tend to develop ovarian cancer at a younger age compared to BRCA2 mutation carriers." (PMID 30174725, 2018). "The aim of this study was to describe genetic variants in the BRCA1 and BRCA2 genes in tumors from Northeast Mexican patients with sporadic ovarian cancer and to detect the percentage of potential eligible patients for future olaparib clinical trials." (PMID 29997359, 2018). "The FDA also approved olaparib as a single agent for the treatment of advanced ovarian cancer patients with germline BRCA1 or BRCA2 mutation who had received three or more prior lines of chemotherapy." (PMID 30050740, 2018). "We have described the genetic variants in BRCA1 and BRCA2 of tumors from Northeast Mexican patients with sporadic ovarian cancers." (PMID 29997359, 2018). "68_69del and c.5266dup) and 1 in BRCA2 (c.5946del)] account for the majority of high risk breast and ovarian cancer cases in that ethnic group." (PMID 30186769, 2018). "Germline pathogenic variants in the BRCA2 gene are associated with a cumulative high risk of breast/ovarian cancer." (PMID 29707112, 2018). "For PCa and ovarian cancer, a BRCA2 mutation accounts for most of the familiarity observed in families of BCa patients." (PMID 29805764, 2018). "BRCA2 N372H polymorphism was found in 40% (4/10) of drug‐resistant recurrent ovarian cancer patients." (PMID 29797793, 2018). "Compound 8 shows antiproliferative activity against a panel of human cancer cell lines, and displays a synergistic effect with cisplatin and paclitaxel in a BRCA2 mutated ovarian cancer cell line, this supporting a possible use for personalized therapy." (PMID 30375481, 2018). "Here, we discuss some key mutations in BRCA1 and BRCA2 that have strong correlation with breast and ovarian cancer and their functional consequences." (PMID 29459887, 2018). "While a previous case report demonstrated a surprising cure of platinum-resistant ovarian cancer with BRCA2 mutation by orally administered melphalan." (PMID 29729664, 2018). "It showed impactful response rates in the BRCA1 or BRCA2-mutated platinum-sensitive ovarian cancer patients." (PMID 30050740, 2018). "Currently, there is consensus that the BRCA1 and BRCA2 mutations are responsible for an average of only 16% of the risk for familial breast and ovarian cancers." (PMID 30135399, 2018). "EMSY is a transcriptional repressor that associates with BRCA2 and is often amplified in breast and ovarian cancers." (PMID 29720118, 2018). "Surveillance is especially critical for women with BRCA1 and BRCA2 mutations due to the increased risk of ovarian cancer." (PMID 29466291, 2018). "We have described genetic variants in BRCA1 and BRCA2 from tumors of Northeast Mexican patients with sporadic ovarian cancer." (PMID 29997359, 2018). "BRCA1 and BRCA2, which were initially named as breast cancer susceptibility genes 1 and 2, are heavily associated with breast and ovarian cancers." (PMID 30551670, 2018). "(2015) showed in a meta‐analysis that BRCA2 N372H polymorphism was associated with a significantly increased risk of ovarian cancer." (PMID 29797793, 2018). "Hereditary breast and ovarian cancer syndrome, which is related to mutations in the BRCA1 and BRCA2 genes, is an important cause of ovarian carcinoma." (PMID 30517521, 2018). "Nonetheless, bilateral salpingo-oophorectomy by age 35 for BRCA1 mutation carriers and 45 for BRCA2 mutation is strongly recommended to prevent ovarian cancer, and has also been shown to impact on survival." (PMID 30572612, 2018).
ovarian carcinoma (continued). "For example, a finding of deleterious mutations in the BRCA1 or BRCA2 genes associates diagnosed women with high frequency of developing breast or ovarian cancer." (PMID 29636096, 2018). "BRCA1 mutations account for about 16.3% of ovarian cancers, and BRCA2 mutations account for 6% of ovarian cancers." (PMID 30551670, 2018). "Pathogenic germline BRCA2 variants predispose to high risk of breast and ovarian cancer and are associated with the Hereditary Breast and Ovarian Cancer syndrome (HBOC)." (PMID 29707112, 2018). "In summary, PARP inhibitors demonstrate a very promising safety profile and anti-tumor efficacy in patients with BRCA1 or BRCA2-mutated platinum-sensitive ovarian cancer patients in both treatment and maintenance settings." (PMID 30050740, 2018). "BRCA1 and BRCA2 mutations are detected in around 5–9% and 3–4% of spontaneous ovarian cancer, respectively." (PMID 30042330, 2018). "Breast cancer susceptibility gene 2 (BRCA2) is key protein that mediates HR, and defects in BRCA2 predispose cells to DNA damage and patients to cancers (particularly breast and ovarian cancers)." (PMID 29757235, 2018). "Constitutional loss-of-function pathogenic variants in the tumor suppressor genes BRCA1 and BRCA2 are widely associated with an elevated risk of ovarian cancer (OC)." (PMID 30441849, 2018). "Mutation of BRCA2 in breast and ovarian cancers compromises DNA homologous repair and then leads to BRCA-associated tumors sensitive to cisplatin, which causes DNA breaks and requires a repair process." (PMID 30001383, 2018). "BRCA1 and BRCA2 germline mutations are the most frequently responsible for hereditary breast and ovarian cancer." (PMID 29882921, 2018). "This reflects an awareness, amongst BWA v3 users, of studies that describe the performance of the model in predicting the likelihood of carrying a BRCA1 or BRCA2 mutation or the risk of developing breast or ovarian cancer in different populations." (PMID 28623477, 2018). "In contrast, some of the women who had a BRCA2 gene mutation decided against the surgery, despite their relatively high risk of getting ovarian cancer." (PMID 30428865, 2018). "As a result of carrying mutations in BRCA1 and BRCA2 women carry a 40% lifetime risk of epithelial ovarian cancer." (PMID 29925418, 2018). "It is important to identify BRCA1 and BRCA2 pathogenic variants in ovarian cancer because they are therapeutic targets for olaparib therapy." (PMID 29997359, 2018). "PARP inhibitors are small molecule inhibitors that have recently been approved for platinum-sensitive relapsed and platinum-resistant ovarian cancers specifically harboring BRCA1 or BRCA2 mutations." (PMID 30551670, 2018). "The aim of this study was to evaluate the prevalence and spectrum of 13 BRCA1 and BRCA2 causative founder variants in unselected patients diagnosed with ovarian cancer from Region of Podkarpacie." (PMID 29492181, 2018). "Causative variants in BRCA1 and BRCA2 are well-established risk factors for breast and ovarian cancer." (PMID 29492181, 2018). "Specifically, even if it is a rare variant (ExAc allele frequency = 0.7%) recently described as associated with an increased risk of developing breast and ovarian cancers, the heterozygous stop gain of BRCA2 (p.K3326X) is considered as “benign” in ClinVar." (PMID 30211214, 2018). "The aim of this study was to describe BRCA1 and BRCA2 gene variants in Mexican patients with ovarian cancer." (PMID 29997359, 2018). "There are also BRCA1 and BRCA2 variants that appear to be associated with a modest or moderate (but still elevated) risk of breast and ovarian cancer, compared with “traditional” deleterious mutations." (PMID 30586411, 2018).
ovarian carcinoma (continued). "Gene predisposition, such as BRCA1 and BRCA2 mutation, also contributes significantly to ovarian cancer." (PMID 30061175, 2018). "The carrier of both the ATM frameshift and BRCA2 K3326* variants developed both breast and ovarian cancer." (PMID 28591191, 2017). "Prospective observational data from the United Kingdom (UK) indicate that the risk of ovarian cancer is much higher among BRCA1 carriers compared with BRCA2 carriers (cumulative risk at age 70 years: 59 versus 17%)." (PMID 28624978, 2017). "Conversely, mutations that lie within the OCCR of BRCA2 predispose carriers to a significantly elevated risk of ovarian cancer compared with other malignancies." (PMID 29228641, 2017). "BRCA1 and BRCA2 are essential for the repair of double-strand DNA breaks, and alterations in these genes are a hallmark of breast and ovarian carcinomas." (PMID 28099152, 2017). "Although the role of BRCA2 has been established in breast and ovarian cancer, the K3326* variant is considered to be benign by commercial testing and therefore was not identified in the initial BRCA1/BRCA2 screening." (PMID 28591191, 2017). "It is well known that BRCA1 and BRCA2 mutations are one of the known risk determinants for the development of ovarian carcinoma and BRCA1/2 mutations is associated with response to platinum-based chemotherapy." (PMID 28978132, 2017). "BRCA1 and BRCA2 germ line mutations increase breast and ovarian cancer susceptibility in heterozygous carriers." (PMID 28729482, 2017). "Germline BRCA1 and BRCA2 mutations account for about 10–15% of ovarian cancers and are mainly found in high-grade serous and endometrioid ovarian carcinomas." (PMID 28073364, 2017). "For individuals with BRCA1 and BRCA2 pathogenic variants, there is a significant risk for breast and ovarian cancer which correlates to the high frequency of contacting family members at genetic risk, both siblings and children." (PMID 28361098, 2017). "Carrying a mutation in the BRCA1 or BRCA2 genes increases a woman’s lifetime risk of developing breast and ovarian cancer, although there are considerable differences in disease manifestation." (PMID 29383107, 2017). "Based on our results, BRCA2 carriers at the 10th percentile of the ovarian cancer PRS have an estimated 6% lifetime risk and approximately 38% of BRCA2 mutation carriers have a lifetime risk of ovarian cancer that is less than 10%." (PMID 28376175, 2017). "Inherited or acquired defects in HR, such as mutations in breast cancer susceptibility protein-1 (BRCA1) or BRCA2, predispose to cancer, including breast and ovarian cancers." (PMID 29145865, 2017). "With the recent introduction of Poly(ADP‐ribose) polymerase inhibitors, a promising novel therapy has become available for ovarian carcinoma (OC) patients with inactivating BRCA1 or BRCA2 mutations in their tumor." (PMID 27767231, 2017). "In the present study, seven deleterious small-range BRCA1/2 mutations were identified in 10% of Colombian breast/ovarian cancer families, including the recurrent BRCA2/1991del4 mutation, which showed a founder origin." (PMID 28680148, 2017). "Carrier status of mutations in BRCA2 is associated with familial breast and ovarian cancer, while bi-allelic BRCA2 mutations can cause Fanconi anemia (FA), a cancer predisposition syndrome with cellular cross-linker hypersensitivity." (PMID 28617445, 2017). "As a result, this PRS had also a higher discriminatory ability for ovarian cancer for BRCA2 carriers compared with BRCA1 mutation carriers." (PMID 28376175, 2017). "BRCA1 and BRCA2 are the most well-known ovarian cancer susceptibility genes, with germline genetic testing available since the 1990s." (PMID 28250960, 2017). "BRCA1,BRCA2, and Lynch mutations increase the lifetime risks of ovarian cancer by as much as 60-, 30-, and 13-fold, respectively." (PMID 28184293, 2017).
ovarian carcinoma (continued). "Second, it is thought that families with a clearly dominant predisposition to breast or ovarian cancer harbor germline mutations in BRCA2 genes." (PMID 28410213, 2017). "Women who carry a pathogenic mutation in the BRCA1 or BRCA2 gene are at high risk of developing breast and ovarian cancers." (PMID 28376175, 2017). "The hazard ratio estimate was larger for ovarian cancer risk in BRCA2 carriers (HR = 1.49, 95% CI = 1.34 to 1.65, P = 8.5×10−14)." (PMID 28376175, 2017). "Germline mutations in BRCA1 and BRCA2 tumor suppressor genes are associated with an increased risk of breast and ovarian cancers." (PMID 28627138, 2017). "A BRCA2 mutation was first detected in breast or ovarian cancer in females and was significantly associated with family history, especially when relatives had breast, ovarian, or prostate cancer." (PMID 28410213, 2017). "Among them, we found BRCA2, transcription factor known for its role in genome stability and which acts as a predisposition gene in breast and ovarian cancers." (PMID 28949986, 2017). "Ovarian cancers in patients with germline mutations in the BRCA1 or BRCA2 genes are more sensitive to DNA damaging agents such as cisplatin." (PMID 28423708, 2017). "Following the identification of a BRCA1/BRCA2 mutation shortly after ovarian cancer diagnosis, the initial focus is often placed on treatment implications for the woman and risks to her relatives." (PMID 28780755, 2017). "Loss of the wild-type BRCA2 allele, indicative of functional inactivation of BRCA2, is common in breast and ovarian cancers arising in BRCA2 mutation carriers." (PMID 28904335, 2017). "The first identified predisposition genes were BRCA1 and BRCA2 with a lifetime penetrance regarding ovarian cancer of 35–59% (BRCA1) and 11–17% (BRCA2), respectively." (PMID 29053726, 2017). "Evaluation of this model with clinical data shows strong overlap with FA-hematopoiesis and BRCA2 associated ovarian cancer." (PMID 28617445, 2017). "The risk of developing breast and ovarian cancer is higher in families that carry mutations in BRCA1 or BRCA2 genes, and timely mutation detection is critical." (PMID 29021639, 2017). "BRCA1 and BRCA2 germline mutation status is known to be associated with improved overall survival in ovarian cancer patients." (PMID 28831036, 2017). "Although they have been associated with an increased risk of occurrence of various other types of cancer that are not of gynecologic origin, the majority of specific inherited mutations in BRCA1 and BRCA2 increase the risk of female breast and ovarian cancers." (PMID 29228641, 2017). "Germline mutations in BRCA1/BRCA2 significantly increase the risk of breast and ovarian cancer in women." (PMID 28780755, 2017). "This is the first evaluation of the combined effects of all known common breast and ovarian cancer susceptibility loci on cancer risks for women who carry a BRCA1 or BRCA2 mutation." (PMID 28376175, 2017). "Lastly, a very recent study uncovered a similar role for the member of the Polycomb Repressive complex 2, EZH2, a histone H3 Lysine 27 methyltransferase, in BRCA2-deficient breast and ovarian cancer cells." (PMID 29355244, 2017). "Given that approximately 560 million East Asians (8% of the world population) carry this mutant allele, our results gain a substantial translational relevance as they predict a low occurrence of BRCA2‐mutated breast and ovarian cancers in this population." (PMID 28729482, 2017). "Olaparib has activity against ovarian cancer in women with germline mutations in BRCA1 or BRCA2, consistent with the synthetic lethality mechanism of PARP inhibitors." (PMID 28525389, 2017). "Pathogenic rare variants of BRCA2 have been found to be associated with hereditary breast and ovarian cancers by the 1000 Genomes dataset." (PMID 28178648, 2017).
ovarian carcinoma (continued). "The ovarian cancer cluster region (OCCR) of BRCA2 has been well defined and studies have shown that mutations outside of the OCCR predispose carriers to malignancies that are not of ovarian origin." (PMID 29228641, 2017). "In Finland, strong founder effects and enrichment of deleterious alleles are seen and major founder mutations in BRCA1 and BRCA2 as well as in other breast and ovarian cancer susceptibility genes account for the vast majority of the identified mutations." (PMID 28874143, 2017). "Questions on the approximate risk of ovarian cancer in women with a BRCA1 or BRCA2 mutation were most frequently answered incorrectly." (PMID 29246147, 2017). "The ovarian cancer risk was 6% by age 80 years for BRCA2 carriers at the 10th percentile of the ovarian cancer PRS compared with 19% risk for those at the 90th percentile of PRS." (PMID 28376175, 2017). "Olaparib has recently been approved for ovarian cancer therapy by the FDA (in 4th line) and European commission (platinum sensitive) to treat patients with ovarian cancer resulting from hereditary BRCA1 or BRCA2 mutations." (PMID 29152107, 2017). "Women who are BRCA1 or BRCA2 mutation carriers face high lifetime risks of breast and ovarian cancer." (PMID 28624978, 2017). "Mutations in the BRCA1 and BRCA2 genes lead to an increased risk of developing breast or ovarian cancer." (PMID 28751759, 2017). "BRCA2 mutations are known to elevate the risk of not only breast and ovarian cancer, but also other cancers like PCa." (PMID 28410213, 2017). "Our results demonstrated that the frequency of BRCA1 and BRCA2 mutations among Chinese women with familial breast/ovarian cancer was 23.3 %." (PMID 26852015, 2016). "Carrying an inherited mutation in the BRCA1 or BRCA2 genes increases a woman's lifetime risk of developing breast and ovarian cancers although there are considerable differences in disease manifestation." (PMID 27015555, 2016). "The PARP-1 inhibitor olaparib is approved for use in BRCA-mutated ovarian cancers but BRCA2-reversion mutations lead to functional homologous recombination repair (HRR) and olaparib resistance." (PMID 26959114, 2016). "Our study suggested that BRCA1 and BRCA2 mutations accounted for a considerable proportion of the hereditary breast/ovarian cancer patients in eastern China and that the spectrum of the mutations in these genes exhibited unique features." (PMID 26852015, 2016). "One of the risk factors for ovarian cancer is germline mutations in BRCA1 or BRCA2 genes, accounting for approximately 8–15% of ovarian cancer cases worldwide." (PMID 27914478, 2016). "In this review, we focus on the Rad52 activities and functions in HR and the possibility of using human RAD52 as therapeutic target in BRCA1 and BRCA2-deficient familial breast cancer and ovarian cancer." (PMID 27649245, 2016). "Germ-line mutations in the tumour suppressor proteins BRCA1 and BRCA2 predispose individuals to breast and ovarian cancer." (PMID 27974137, 2016). "A total of 10 deleterious mutations in BRCA2 were found in 13 familial breast/ovarian cancer patients in this cohort." (PMID 26852015, 2016). "The estimated lifetime risk of ovarian cancer in BRCA1 mutation carriers is 40% to 50%, among BRCA2 mutation carriers the risk is lower, ranging from 20% to 30%, while the lifetime risk of ovarian cancer in the general population is 1.6%." (PMID 27350785, 2016). "BRCA1 and BRCA2 are the most important genetic susceptibility genes for breast/ovarian cancer in both Caucasian and Chinese populations." (PMID 26852015, 2016). "Some commentaries on the potential role of BRCA2 mutations as a real prognostic factor in ovarian cancer patients show such a particular role of patient selection and differences in surgical and oncologic managements." (PMID 26753012, 2016). "One of the mutations found in BRCA2 gene, c.9076C>T/p.Gln3026Ter, has previously been identified in Japanese families with a history of breast or ovarian cancer." (PMID 27732944, 2016).